GPSM3 (G protein signaling modulator 3)
Description:
Interacts with subunit of G(i) alpha proteins and regulates the activation of G(i) alpha proteins.
Synonyms: AGS4; C6orf9; G18; NG1; G18.1a; G18.1b; G18.2
Tractability: Antibody: its Gene Ontology location is reachable by antibodies, with medium confidence. PROTAC: its protein half-life has been measured.
Gene: Protein-coding gene on chromosome 6 (32,190,766 to 32,195,523, reverse strand). Ensembl gene ENSG00000213654.
Subcellular location: Cytoplasm
Pathways (Reactome):
Signal Transduction: G alpha (i) signalling events
Gene Ontology:
Molecular function: protein binding; GTPase regulator activity
Biological process: positive regulation of inflammatory response; regulation of inflammatory response
Cellular component: cytoplasm; plasma membrane
Genetic constraint (gnomAD): Loss-of-function variants: 16 observed, 16.83 expected, observed/expected ratio (o/e) 0.95, 90% interval 0.64 to 1.44. The upper end of that interval is the gene's LOEUF score, 1.44, which puts it in group 5 of 6, group 1 being the genes least tolerant of losing a copy. Missense variants: 177 observed, 188.14 expected, observed/expected ratio (o/e) 0.94, 90% interval 0.83 to 1.07. Synonymous variants: 70 observed, 70.07 expected, observed/expected ratio (o/e) 1, 90% interval 0.82 to 1.22.
Homologues: Orthologues: chimpanzee GPSM3 (100% identical), macaque GPSM3 (98% identical), dog GPSM3 (91% identical), rabbit GPSM3 (90% identical), mouse Gpsm3 (88% identical), pig GPSM3 (88% identical). Paralogues in human: GPSM2 (35% identical), GPSM1 (31% identical), TTC28 (25% identical), TTC24 (14% identical), RAPSN (9% identical), TTC29 (9% identical).
Diseases named in the same sentence as GPSM3 in open-access papers:
GPSM3 is named in the same sentence as 21 diseases in open-access papers, as found by Europe PMC text mining. Sharing a sentence is not in itself a finding about the gene and the disease. The quoted sentences say what the papers report.
autoimmune disease (5 papers, 2018 to 2025). A disorder resulting from loss of function or tissue destruction of an organ or multiple organs, arising from humoral or cellular immune responses of the individual to their own tissue constituents. "GPSM3 (G protein signaling modulator 3) is an MHC-regulated gene bearing alleles that protect against severe autoimmune diseases." (PMID 40075650, 2025). "GPSM3 in turn has a selective immune cell expression distribution and SNPs in this gene have been associated with autoimmune diseases." (PMID 34526996, 2021). "The MMP13 and GPSM3 genes play significant roles in rheumatoid arthritis in humans, and the GPSM3 gene has been associated with the risk of developing autoimmune diseases." (PMID 30648118, 2018). "Human GWAS studies have pointed to an inverse correlation between GPSM3 and autoimmune diseases, demonstrating that polymorphisms in this gene were associated with the decreased incidence of immune-mediated diseases such as rheumatoid arthritis and systemic lupus erythematosus (SLE)." (PMID 34440439, 2021). "Previous research has indicated that GPSM3 is important in inflammation and autoimmune diseases, including rheumatoid arthritis and ankylosing spondylitis." (PMID 34572330, 2021).
Autoimmunity (2 papers, 2017 to 2021). The occurrence of an immune reaction against the organism's own cells or tissues. "GPSM3 is upregulated when the level of myeloid-derived suppressor cells (MDSCs) expands, which again is correlated to increased levels of autoimmunity or inflammation." (PMID 34526996, 2021).
Arthritis (1 paper, 2018). Inflammation of a joint. "Additionally, mice deficient for the Gpsm3 gene were protected from arthritis induced by anticollagen antibodies that reduced CCL2 and CX3CL1-mediated migration of myeloid cells." (PMID 30648118, 2018).
breast carcinoma (1 paper, 2021). "GPSM3, alternatively known as AGS4 or G18, encodes for the activator of G-protein signaling 4, and was found to be overexpressed in breast cancer in our study." (PMID 34572330, 2021). "We further clarify the association between GPSM3 expression and immune infiltrates in different subtypes of breast cancer." (PMID 34572330, 2021). "Similar analyses of GPSM1, GPSM3, and GPSM4 showed that their related biological pathways are only minimally linked to breast cancer development." (PMID 34572330, 2021). "Taken together, it is suggested that GPSM3 expression was related to immune infiltration levels in breast cancer." (PMID 34572330, 2021). "In this study, we propose that GPSM3 plays a potential role in the diagnosis and inflammation in breast cancer." (PMID 34572330, 2021). "To summarize, our study proposed GPSM2 as a potential progsnotic marker and therapeutic target, and GPSM3 as a possible target for immunotherapy for breast cancer." (PMID 34572330, 2021). "Furthermore, GPSM3 has potential to be a possible target for immunotherapy for breast cancer." (PMID 34572330, 2021). "The results demonstrated that GPSM3 expression was most strongly correlated with levels of CD8+ T cells, B cells, macrophage, and myeloid dendritic cells in subtypes basal and HER2 of breast cancer." (PMID 34572330, 2021).
colitis (1 paper, 2017). Inflammation of the colon. "In the Gpsm3−/−and Dock2−/− colitis models, the colon weight/length ratio was significantly higher than that in wild-type mice." (PMID 28892060, 2017).
glioblastoma multiforme (1 paper, 2024). "Recent studies indicate that GPSM3 may play a crucial role in treating inflammatory diseases and cancer, particularly in the context of glioblastoma multiforme (GBM)." (PMID 38674408, 2024).
glioma (1 paper, 2021). A benign or malignant brain and spinal cord tumor that arises from glial cells (astrocytes, oligodendrocytes, ependymal cells). "It is well-known that isocitrate dehydrogenase (IDH) status and 1p19q codeletion influence the prognosis of gliomas; thus, we determined the expression patterns of GPSM3 based on IDH status and 1p19q codeletion." (PMID 34827528, 2021). "In this study, we first assessed the expression patterns and clinical characteristics of GPSM3 in LGG to determine its potential functions and prognostic values based on data from The Cancer Genome Atlas (TCGA) datasets and the Chinese Gliomas Genome Atlas (CGGA) datasets." (PMID 34827528, 2021). "The results showed that the expression of GPSM3 was significantly upregulated in the IDH wild-type LGG and 1p19q codeletion LGG compared to that in IDH-mutant gliomas and 1p19q non-codeletion LGG." (PMID 34827528, 2021).
multiple sclerosis (1 paper, 2025). A progressive autoimmune disorder affecting the central nervous system resulting in demyelination. "Furthermore, it was verified that GPSM3 was associated with to particular SNPS (rs204989 and rs204991), and via causing neutrophil migration, GPSM3 was related to a lower risk of RA, AS, SLE, Type 1 diabetes and multiple sclerosis." (PMID 39789419, 2025).
myocardial infarction (1 paper, 2020). Gross necrosis of the myocardium, as a result of interruption of the blood supply to the area, as in coronary thrombosis. "In our previous study, we found that small G protein signaling modulator 3 (SGSM3), a partner of Cx43, contributes to myocardial infarction (MI) in rat hearts." (PMID 32271805, 2020).
rheumatic diseases (1 paper, 2025). "It has been discovered that some of these genes (C2, BX511262.2, PRRC2A, BAG6, PBX2, GPSM3, NELFE and AIF1) are significant genetic targets shared by MetS and multiple rheumatic diseases." (PMID 39789419, 2025).
triple-negative breast carcinoma (1 paper, 2021). An invasive breast carcinoma which is negative for expression of estrogen receptor (ER), progesterone receptor (PR), and human epidermal growth factor receptor 2 (HER2). "GPSM1, GPSM2, and GPSM3 were most highly expressed in triple negative breast cancer cell lines, while GPSM4 showed high expression in multiple luminal A cell lines." (PMID 34572330, 2021).
cancer (4 papers, 2011 to 2024). A tumor composed of atypical neoplastic, often pleomorphic cells that invade other tissues. "We first performed a pan-cancer analysis of GPSM3 in UCSCXenaShiny, and the results showed a significant difference in GPSM3 mRNA levels between a variety of tumors and normal tissues." (PMID 34827528, 2021). "Given the importance of immunotherapy in cancers, we analyzed the correlation between GPSM3 and immune checkpoint genes in the TCGA-LGG and CGGA-LGG datasets." (PMID 34827528, 2021). "In the present study, we first performed a pan-cancer analysis in UCSCXenaShiny to explore the role of GPSM3 in cancers and observed that GPSM3is highly expressed in a variety of cancers, which may indicate its crucial role in cancers." (PMID 34827528, 2021). "However, the functions of GPSM3 in malignant tumors remain unclear." (PMID 34339395, 2021).
tumor (4 papers, 2021 to 2024). "Functional characterization of GPSM3 revealed that it was associated with many immune processes to tumor cells." (PMID 34827528, 2021). "However, the role of GPSM3 in tumor progression and the underlying molecular mechanisms are poorly understood." (PMID 34827528, 2021). "The results showed that GPSM3 expression was positively related to the immune score, stromal scores, and ESTIMATE scores, but negatively related to tumor purity, indicating that the expression of GPSM3 plays a regulatory role in the TME component in LGG." (PMID 34827528, 2021). "GPSM3 was found to be up-regulated in normal samples and the cases with favorable prognosis, indicating GPSM3 acted as a tumor suppressor for BCa." (PMID 34339395, 2021). "Subsequently, we confirmed the higher expression of GPSM3 in LGG using two different tumor databases, GEPIA and ONCOMINE." (PMID 34827528, 2021). "Specifically, GPSM3 has emerged as a promising target for immunotherapy in GBM patients, due to its strong correlation with immune checkpoints and tumor microenvironment (TME) immunosuppressors in GBM." (PMID 38674408, 2024). "The results showed that GPSM3 expression was positively related to the immune score, stromal scores, and ESTIMATE scores in the TCGA dataset, but negatively correlated with tumor purity." (PMID 34827528, 2021). "GPSM3 expression was positive related to the immune score, Stromal scores and ESTIMATE scores, but negative related to the Tumor purity." (PMID 34827528, 2021).
GPSM3 also shares sentences with these, for which no sentence is quoted: rheumatoid arthritis (3 papers); ankylosing spondylitis (1); atherosclerosis (1); fibrosis (1); leukocytosis (1); neutropenia (1); systemic lupus erythematosus (1); Type 1 diabetes (1).